CD4 (CD4 molecule)
Diseases named in the same sentence as CD4 in open-access papers (continued):
Sharing a sentence is not in itself a finding about the gene and the disease.
infection (continued). "Unconventional T cells and innate lymphoid cells, particularly NK cells, were the dominant producers of early Ifnγ, while CD4 and CD8 T cells were the main producers by day 10 post-infection." (PMID 37842651, 2023). "This elevated type-2 inflammatory response was also evident in BAL cellular influx, with numeric and proportional increase in BAL eosinophils, CD4+ and CD8+ T cells during patent infection, patterns seen to a lesser extent in pre-patent infection." (PMID 37012228, 2023). "Prior to infection and before administration of CD4R1, circulating CD4+ T-cell counts were similar between the CD4+-cell-depleted AGMs and controls (241 ± 70 and 248 ± 106 cells/μL, respectively)." (PMID 36813761, 2023). "The presence of SARS-CoV-2-responding CD4+ T cells primarily exhibiting a monofunctional profile observed in seronegative children led us to hypothesize that the T cell response could be due to cross-reactivity resulting from prior infection with common circulating endemic HCoVs." (PMID 37292954, 2023). "At the same time, the relatively small share of E/TE CD4+ and CD8+ virus-specific T corroborated with the low share of positive results in IFNγ ELISpot assay beyond 9 months post-infection." (PMID 37046496, 2023). "We isolated CD4 + CD45RO- naïve resting T cells and CD4 + CD45RA- memory resting T cells from the same donor, and co-cultured them with IEC one day before infection." (PMID 37202790, 2023). "Both SARS-CoV-2-specific CD4+ and CD8+ memory T cells peaked within the initial month of infection, followed by a gradual decline over the subsequent 6 to 7 months." (PMID 37936709, 2023). "Upon challenge, MCMV boosted animals had increased serum IL-12 and a larger CD4 polyclonal effector T cell response, which were reduced by neutralization of IFN-γ before infection." (PMID 37205446, 2023). "B. bronchiseptica infection induced > 2-fold increase in numbers of CD4+ and CD8+ cells in both the nasal cavities and the MEs, demonstrating similar recruitment and/or expansion of lymphoid cells in response to infections at these sites." (PMID 38125908, 2023). "Analysis of brain leukocytes in Lm 10403s-infected mice showed significant brain influxes of CD4+ and CD8+ T-lymphocytes, including sub-populations expressing the CD69 activation marker and TRM markers, as well as granulocytes, 1 mo after infection." (PMID 37143648, 2023). "Consistent with our previous findings, we found higher numbers of CD3+, CD4+, CD8+, and γδ T cells in dLNs 1 week after infection in mice that received ADAM10i prior to infection, compared with those that received vehicle (DMSO) alone." (PMID 36693884, 2023). "All three of these arms (antibodies, CD4+, and CD8+) work together to combat infection with SARS-CoV-2, and follow the recognition of the virus by dendritic cells, and migration of those activated dendritic cells to lymph nodes." (PMID 37404823, 2023). "Correlation between the percentage of FAM-FLICA+ CD4+ (E), CD8+ (F) splenic cells and IL-18 plasma levels in vehicle treated HIV-1 infect group at day 22 post-infection." (PMID 36800238, 2023). "During meningitis caused by E30 infection, viruses may interact with two major CNS barriers: the blood–brain barrier (BBB) and the blood cerebrospinal fluid barrier (BCSFB), while E30 infection has been shown to increase the migration of naïve T cells, including CD3+, CD4+, and CD8+, in the BCSFB." (PMID 37485505, 2023). "Infection of these mice with HTLV-1 results in integration of the virus into the genome of human lymphocytes, followed by activation and proliferation of CD4+ T-cells." (PMID 36819050, 2023). "To assess the impact of the treat-all policy, we analyzed the time from diagnosis to ART initiation, the CD4 + T-cell count at ART initiation, and the mean estimated time from infection to diagnosis." (PMID 37580822, 2023). "Interferons (IFNs), CD4+ and CD8+ T cells are important in the recovery from infection with ectromelia, a mousepox virus." (PMID 37925424, 2023).
infection (continued). "Although both HHV6-A and-B strains infect CD4 + T helper and CD8+ cytotoxic T cells, upon infection, HHV6 selectively suppresses the expression of IL12 and inhibits Th1 polarization of CD4 + T cells." (PMID 36750846, 2023). "Sex steroids acting via ER or AR elicit both direct and indirect effects on CD4+ and CD8+ T cell function in diverse models of infection, autoimmunity and cancer." (PMID 37063266, 2023). "Accordingly, in the present study we found that liposomal LiChimera was highly immunogenic since it was able to elicit antigen-specific TH1-type CD4+ and CD8+ T cells in the spleen that contributed to the control of infection." (PMID 37631952, 2023). "With peripheral CD4+CD8+DPT cells as protective immune cells, it can be inferred that PA-MSHA has an immunomodulatory and protective effect on PCNL patients with infection." (PMID 37377966, 2023). "By day 4 post-infection, we detected activated virus-specific CD8+ and CD4+ T cells in the infected skin, with most gDT-II CD4+ T cells displaying Th2 (GATA3+) and Th17 (RORγt+) phenotypes." (PMID 37371900, 2023). "In this paper, we aimed to further understand the role of HBV antigenemia (i.e., HBs- and HBeAg levels) on the liver immune environment to define key CD4 and CD8 T-cell populations and their ability to control the infection upon vaccination." (PMID 38140229, 2023). "Our cats demonstrated successful infection from FIV-C with infectivity similar to a previous experimental FIV model, with analogous patterns in neutrophil, FIV provirus, and CD4+ changes." (PMID 37112803, 2023). "After a primary infection in SOT recipients, CMV-specific CD4+ T cells can be detected 1 week after the occurrence of CMV DNAemia, more specifically those CD4+ CD28-granzyme B+ cells." (PMID 38020746, 2023). "In other infections, such as Bacillus Calmette-Guerin (BCG), dermal IL-17-producing γδ T cells increase CD4+ T cell proliferation by inducing neutrophil recruitment, which contributes to antigen delivery to the dLN." (PMID 38124746, 2023). "Studies have shown that when animals suffer from CTX, the secretion levels of CD3+, CD4+, CD8+, and CD4+/CD8+ are reduced, resulting in an imbalance of Th1/Th2 cell proportion, decreased immune function, and induced secondary infection." (PMID 37958131, 2023). "In an experimental model of murine alveolar echinococcosis (E. multilocularis) infection, anti-PD-L1 administration results in increased CD4+/CD8+ effector T cells and decrease of T regs, as an improved control of the infection." (PMID 37764924, 2023). "In connection with the fact that CD4+ T cells act as reservoirs for latent HIV, infection with M. tuberculosis induces HIV to exit the reservoirs and reduces CD4+ cell counts." (PMID 37606452, 2023). "In this paper, we identify ZIKV-specific CD4+ and CD8+ T cell epitopes that induce responses during infection." (PMID 37705976, 2023). "We observed several interesting details when we analyzed the dynamics of CD4+ and CD8+ cell counts and viral load during the course of infection." (PMID 36674980, 2023). "Upon infection with SARS-CoV-2, those able to generate immune responses using B cells, CD4+ cells, and CD8+ cells are able to limit disease severity." (PMID 37404823, 2023). "In both cis- and trans-infection, HIV particles are transferred from donor cells (DCs or Mø) to receptor cells (CD4+ T lymphocytes) by a cell-to-cell synapse-induced mechanism." (PMID 37243118, 2023). "Collectively, these data demonstrated that CD4+ T-cell activation was significantly increased during breakthrough infection in the ZF2001 booster group, in line with the obvious increase in HIV reservoir size and decreased CD4 counts." (PMID 38140668, 2023). "Infected CD4+ helper and CD8+ cytotoxic T cells (Th and Tc, respectively) were detected at 4 dpi; infection peaked 2 d later." (PMID 37377421, 2023).
infection (continued). "The TZM.bl cells used for neutralization assays are HIV-1 permissive reporter HeLa cells modified to express the receptor (human CD4) and co-receptors (human CCR5 and CXCR4), allowing the virus to initiate infection in these cells." (PMID 37681958, 2023). "CD4 and CD8 T cells represented the majority of T-cell populations in WildR and LabC mice during infection." (PMID 37494371, 2023). "CD4+ T-cell counts and HIV viral load are two biomarkers routinely collected from HIV-positive patients to monitor infection and treatment response." (PMID 37438354, 2023). "Conventional HIV infection involves virus binding to the CD4 receptor, followed by interaction with co-receptors such as CCR5 or CXCR4 on CD4+ T lymphocytes to initiate direct infection or cis infection." (PMID 37808906, 2023). "Increased cholesterol efflux in APCs isolated from NPs inhibits HIV-1 trans-infection, while reconstitution of the cholesterol content in membranes from NP myeloid DCs and B cells restores their capacity to HIV-1 trans-infect CD4+ T cells." (PMID 38140588, 2023). "On adjusted median regression analysis, in comparison to healthy controls, there was similar frequency of activated CD4+ T cells (P = .37) and CD8+ T cells (P = .67) post–BT infection in patients with HM." (PMID 38023562, 2023). "When exposed to a live infection, CD4 and CD8 T cells respond considerably differently, which supports the theory that the early phases of Mtb infection are dominated by the CD4 T cells’ immune response." (PMID 37111338, 2023). "After 40 days of infection, the hidden public TCR changed their dynamics, CD4+ reduced, and CD8+ maintained high frequency." (PMID 37325645, 2023). "The abundance distribution profile of the repertoires showed the presence of highly expanded TCRs in the spleen of both CD8+ and CD4+ effector, and in CD8+ central memory T cells 8 days following infection." (PMID 37325645, 2023). "Conversely, the activation and proliferation of T-cells were negatively correlated with epithelial markers, as CD4+ and CD8+ T-cells were activated and started proliferating after infection." (PMID 36639424, 2023). "At day 14 p.i., we sorted CD45.1+CD45.2+CD44+Tigit+IL-7Rα–PD-1+CXCR5+ and CD45.1+CD44+Tigit–IL-7Rα+PD-1+CXCR5+ CD4+ T cells and co-transferred them into CD45.2+ recipient mice followed by PR8 infection." (PMID 37330549, 2023). "In further analysis of infection-naïve individuals by ICS, lower CD4+ and CD8+ IFNγ and TNF responses to Delta S peptide pools were found among cases compared to controls." (PMID 37655880, 2023). "Protective immune responses against symptomatic IFAV infections that are likely to eliminate infection in the URT have innate (e.g., IFNs) and adaptive (e.g., IgA and IgG antibodies, tissue-resident memory CD8+ TC and CD4+ TH cells) immunity components." (PMID 38005881, 2023). "This indicates that CD4+ T cells are essential for the control and clearance of TAS2010 growth as the primary infection." (PMID 37733817, 2023). "The elimination of both CD4+ and CD8+ T cells after 6 weeks of infection increases the fungal burden, showing the influence of these cells on reactivation." (PMID 36836308, 2023). "The CD4+ and CD8+ T-cell responses exhibited comparable levels between mRNA vaccination and infection, with similar T-cell production observed at both 6 months after the second dose and 6 months post-infection." (PMID 37936709, 2023). "These include the effector CD4+ T helper 1 (TH1), T follicular helper (TFH), and cytotoxic subsets, each of which perform distinct activities to eliminate infection." (PMID 36964178, 2023). "The numbers of multifunctional cytokine+ CD4 T cell that produced IFN‐γ, IL‐2 and TNF were particularly stable between days 9 and 30 post‐infection." (PMID 37490492, 2023). "Later, between months 3 and 6 after KT, patients who subsequently presented with infection had lower CD3+ T cells and lower CD4+ T cells." (PMID 37515152, 2023).
infection (continued). "Compared to the pre-infection timepoint, a significant increase in the activation of CD4+ TN and CD8+ TCM was found in the BBIBP-CorV individuals, whereas higher CD4+ TN activation was observed in the ZF2001 booster group." (PMID 38140668, 2023). "73.9% of patients has been diagnosed for more than 1 year, 46% is 30–39 years, 61.5% has college education or above, 12.8% is unemployed, 5.4% and 23.6% has abnormal CD4+ or CD4+/CD8+ ratio, respectively, for more than one year of infection." (PMID 36700040, 2023). "Researchers reported that Th1 CD4+ T cells play an important role in the control of Brucella infection, but bacterial clearance by CD8+ T cells during primary infection importance can be neglected." (PMID 37051103, 2023). "Previous MDV studies revealed that challenging chickens with MDV upregulates IL-10 expression in the spleen, including in splenic CD4+ T cells, CD8+ T cells, and γδ T cells at the later phase of infection." (PMID 36851499, 2023). "The infection site control is, as expected, IFN-γ dependent and is primarily mediated by CD4+ T cells, the latter perhaps reflective of the fact that most of the infected cells at the site are capable of expressing class II MHC." (PMID 36695605, 2023). "In previous studies, we have shown that at different stages of infection after E. multilocularis challenge, hepatic CD4+ T cells express significant amounts of LAG3; LAG3+CD4+ T cells secrete less IFN-γ." (PMID 37172058, 2023). "In contrast, a moderate but significant increase in the fraction of CD4+ TEM was observed in both blood and LN of RMs belonging to the ‘pre-infection’ CD8+ depletion group." (PMID 36690860, 2023). "Infection levels in IEC-stimulated CD4 + T cells can achieve 40–50%, compared with < 10% in unstimulated CD4 + T cells." (PMID 37202790, 2023). "Similar to observations in the mouse, we found that OX40 was predominantly expressed on CD4+ T cells, with far less frequent expression on CD8 T cells at the site of infection." (PMID 38110410, 2023). "At 6 months post-infection, SARS-CoV-2-specific memory CD4+ and CD8+ T cell responses were established in 90% and 70% of tested subjects, respectively, and their half-lives were estimated to be about 3–5 months." (PMID 37046496, 2023). "CD4+ and CD8+ T-cell populations were systemically depleted by administering antibodies to mice 24 h prior to infection with rVSV-EBOV GP." (PMID 37376652, 2023). "T-cell activation during infection happens through the T-cell receptor (TCR), which includes the CD3 receptor and either the CD4 or CD8 co-receptors." (PMID 38093984, 2023). "At the chronic phase of infection after viral clearance, CMV-specific CD4+ T cells represent up to 9% of the memory T lymphocyte pool." (PMID 38020746, 2023). "In line with this, the percentage frequency of CD4+ T cells that produce IFN-γ, IL-17 or IL-10 in the splenocytes remained low in BA.5 infection as compared to ancestral Wuhan-Hu-1, but were found to be comparable to that of parental B.1.1.529 infected mice." (PMID 37704701, 2023). "In older birds, CD4+TGFβ+ cells and CD4+CD25+TGFβ+ cells were present at earlier time points, from 7dpi following 228E infection, and from 14 and 28 dpi following F52/70 infection, respectively." (PMID 37744374, 2023). "First, vaginal LCs were exposed to HIV-1 for 2 days, allowing productive infection of LCs, then washed extensively and subsequently co-cultured with PHA/IL2-activated CD4 T cells in a 1:2 ratio for 3 days." (PMID 36841916, 2023). "While the overall pattern of T cell movements was consistent with CRWs, there were differences between CD4 and CD8 T cells in details of the movement and how the movement was impacted by the time since infection." (PMID 37811200, 2023). "Susceptibility to HIV-1 is also regulated by a cell's metabolic activity and activation stage, where CD4+ T cells with elevated OXPHOS and glycolysis are more permissive to infection." (PMID 36779490, 2023).
infection (continued). "Percentage and MFI of FAM-FLICA+ CD4+ (A, C), CD8+ (B, D) splenic cells in vehicle or VX-765 treated HIV-1 infected huNSG mice at day 22 post-infection." (PMID 36800238, 2023). "The absolute CD4 counts decreased in the heterologous group, whereas the CD8 counts decreased in the homologous booster group after breakthrough infection in PLWH." (PMID 38140668, 2023). "After one day, CD4 + T cells cultured alone, stimulated by IEC, with or without anti-CD2 antibody, were infected, and GFP levels were measured on day 6 post-infection." (PMID 37202790, 2023). "Elegant longitudinal studies demonstrated that both effector memory CD4+ and CD8+ T cells are induced after exposure to DENV and that these cells are long-lived, persisting for 12 months post-infection." (PMID 37055751, 2023). "Our study reveals benign characteristics including the overall higher baseline CD4+ T cell count and baseline CD4+ T/CD8+ T ratio, especially a very low proportion of X4-tropism in infections of CRF07_BC." (PMID 37152735, 2023). "The role of cholesterol metabolism in trans-infection, therefore, requires deeper exploration to unravel the mechanism by which it modulates the transfer of HIV-1 from APCs to CD4+ T cells." (PMID 38140588, 2023). "Strikingly, PLWH had a significant increase in the activation of CD4+ TN, CD4+ TCM, and CD8+ TCM after the breakthrough infection." (PMID 38140668, 2023). "This is the first study to characterize CD4+ and CD8+ T cell populations over the course of infection using an NHP model of pediatric TB and HIV/Mtb coinfection." (PMID 37039653, 2023). "Two other studies reported that SARS-CoV-2 specific CD4+ and CD8+ T cell responses remained detectable more than 10 months post infection." (PMID 37508464, 2023). "In unvaccinated individuals with prior infection, we found signs of coordination between T-cell (cellular) and antibody (humoral) responses to SARS-CoV-2 antigens, and between CD4+ and CD8+ T-cell compartments." (PMID 37220145, 2023). "In support of a role for Hla in impairing expansion of T cell populations, there were higher numbers of CD3+, CD4+, CD8+, and γδ T cells in dLNs of mice that received Hla-specific antiserum prior to infection, compared with those that received naïve serum." (PMID 36693884, 2023). "Further, we identified PD-1+ Tex subsets within both CD4+ and CD8+ T-cell compartments based on CXCR5 and TIM-3 expressions in lymph nodes and infection sites." (PMID 37691941, 2023). "Altogether these results suggest that differences in polyfunctional CD4+ T cells cannot be attributed only to CKD condition but also to other factors including immunosuppressive regimens and natural infection, among others." (PMID 37243116, 2023). "Next, we assessed polyfunctionality of vaccine-induced SARS-CoV-2-specific CD4+ T cells, as multifunctional Th1 cells (IFN-γ+TNF-α+IL-2+) have been described to provide a better correlate of immune protection against infection after vaccination." (PMID 37199415, 2023). "To determine the changes of CD4+ and CD8+ T-cell subset composition among PLWH during breakthrough infection, we used flow cytometry to analyze T-cell subsets according to the expression of CD45RA, CD27, and CCR7." (PMID 38140668, 2023). "The absolute cell count of CXCR5+TIM-3+ and TIM-3+ cells of CD4+ and CD8+ T-cell compartments significantly increased from day 30 to 60, and remained high at least until day 90 of infection." (PMID 37691941, 2023). "We hypothesize these changes might be linked with phenotypic changes in the total pool of CD4+ T cells and to intra-host viral evolution, rather than variation in integration sites landscapes, as these were recently shown not to vary during infection and after ART." (PMID 38420260, 2023). "In this study, we observed a significant decline in CD4 counts and a partially increased HIV reservoir after breakthrough infection." (PMID 38140668, 2023).